IDH1 (isocitrate dehydrogenase (NADP(+)) 1)
Diseases named in the same sentence as IDH1 in open-access papers (continued):
Sharing a sentence is not in itself a finding about the gene and the disease.
glioma (continued). "IDH1-mutant glioma patients typically exhibit enhanced responsiveness to temozolomide (TMZ) chemotherapy, along with significantly improved prognoses compared to those with IDH1 wild-type tumors." (PMID 38982076, 2024). "Immunohistochemical markers such as isocitrate dehydrogenase 1 (IDH1) and alpha thalassemia/mental retardation syndrome X-linked (ATRX) can be used for the diagnosis and prognosis of the majority of gliomas." (PMID 39192927, 2024). "Mutations in PIK3CA p.E545K and amplification in ERBB2 were common in breast cancers, BRAF p.V600E in metastatic melanoma and IDH1 p.R132H in IDH-mutant gliomas." (PMID 39289779, 2024). "Compared with IDH-1 wild-type (IDH-1(-)), the glioma patients with IDH-1 mutant-type (IDH-1(+)) have longer survival time and better efficacy of chemoradiotherapy." (PMID 39285364, 2024). "Herein, we conducted a retrospective clinical investigation to confirm that IDH1-mutant glioma patients indeed exhibited improved prognoses, greater responsiveness to TMZ treatment, and elevations of D-2HG in comparison to those with IDH1 wild-type gliomas." (PMID 38982076, 2024). "IDH1 and IDH2 mutations are also associated with a better prognosis and are often found in lower-grade gliomas and secondary GBMs, which generally progress more slowly than primary GBMs." (PMID 39767571, 2024). "We also found in both IDH1 MT glioma cell lines and a murine glioma model that VPA inhibited the mTOR pathway, and downregulated FASN mRNA and protein expression." (PMID 39149696, 2024). "To investigate the impact of co-occurring IDH1 and ATRX mutations on innate immune signaling in glioma, we generated CT2A cells expressing mutant IDH1R132H in both AtrxWT and Atrx-KO genetic backgrounds." (PMID 38272925, 2024). "We analysed brain tissue sections from mice that had been orthotopically implanted with GL261 glioma cells expressing mutant isocitrate dehydrogenase 1 (IDH1) and red fluorescent protein (RFP)." (PMID 39251875, 2024). "Of pathogenetic significance was the additional disruption of the genomic locus rs55705857, which increases penetrance and decreases latency of Idh1(R132H)‐driven glioma." (PMID 39324445, 2024). "According to the 2021 Classification of the Central Nervous System Tumors of the World Health Organization, all of the included patients in our study presented with IDH-1 wild type." (PMID 38539563, 2024). "To align with the 2021 WHO classification of tumors of the central nervous system 38, we further examined the IDH1 status and chromosome 1p/19q status of the patients." (PMID 38994023, 2024). "Research showed different molecular markers in tumors between children and adults, with pediatric low-grade gliomas predominantly exhibiting alterations in the BRAF, FGFR, and MYB/MYBL1 genes, while IDH1/2 mutations were less common." (PMID 38137148, 2023). "While 2HG production contributed to such impairment in an experimental glioma, this raised the unexplored possibility that wild-type IDH1 is a tumor-derived immune enhancing factor." (PMID 37161052, 2023). "In this study we investigate the effect of the IDH1 mutation on H3K27 acetylation and determine which HDAC genes are essential for growth in patient derived IDH1 mutant glioma cells." (PMID 37528157, 2023). "Phase I and II trials involving the use of a selective mutant IDH1 inhibitor (DS-1001) for the treatment of recurrent IDH-mutant gliomas have been conducted." (PMID 37372381, 2023). "Together, these findings broadly support the notion that glioma killing by CTL is modulated by cytoplasmic IDH1 proteins released from lysed tumor cells." (PMID 37161052, 2023). "Expression of innate and other adaptive immune genes, including GFAP for activated astrocytes and IBA-1 for microgliosis, were comparable between IDH1R132H and IDH1-wild-type gliomas." (PMID 37161052, 2023).
glioma (continued). "This study demonstrated that, at least in this model, targeting mutant IDH1 can impair glioma development in vivo, which is related to changes in cellular differentiation." (PMID 37296846, 2023). "This correlation of PRMT1 and PTX3 with ferritinophagic markers is conserved in gliomas of diverse genetic landscape and shows prognostic value in IDH1 mutant glioma patients." (PMID 37476290, 2023). "The heat map shows higher expression of NDUFB2 list in the high-grade glioma, classical subtype, and IDH-1 wild-type groups, and the trend is similar is other related genes." (PMID 36860730, 2023). "Transwell assay and monolayer cell migration scratch assay also showed that IDH1-mutant glioma cells reduced migration and invasion capabilities." (PMID 37952042, 2023). "A critical role for αKG-dependent epigenetic modulation in CSC has been demonstrated in glioma-initiating cells, in which upregulation of wild-type IDH1 activates oxidative decarboxylation of citrate to increase αKG levels." (PMID 36768660, 2023). "Univariate analysis showed that compared to IDH1 wild-type glioma, IDH1-mutant glioma correlated significantly with a longer survival time after the first operation." (PMID 36597096, 2023). "The lowest recurrence rate (3/8) of IDH1 (R132H) U87 tumor was achieved and the survival rate of mice reached to 82.5% within 60 days, providing a good paradigm for the post‐surgical treatment of IDH1 (R132H) glioma." (PMID 38264686, 2023). "Hypoxia has been shown to increase SCD expression through SREBP-1, and IDH1 mutation increases SCD expression through the oncometabolite D-2-hydroxyglutarate, mainly in low-grade glioma and secondary glioblastoma where these mutations are common." (PMID 37046844, 2023). "EVs from glioma patients have been shown to be a source for the detection of clinically relevant prognostic biomarkers, such as IDH1-R132H and EGFRvIII, and have been successfully extracted from blood and CSF." (PMID 37568598, 2023). "Diffuse gliomas with IDH1/2, H3F3A (Histone H3 Family 3A) and HIST1H3B/C wildtype status are classified as glioblastoma." (PMID 37444635, 2023). "Ten glioma samples (5 IDH1 wildtype and 5 IDH1 mutant) were stained for various HDAC genes using internally validated antibodies (HDAC1, HDAC2, HDAC3, HDAC4, HDAC5, HDAC6 and HDAC7) and scored by a blinded neuropathologist (AK)." (PMID 37528157, 2023). "In this retrospective study, patients with a diagnosis of IDH1 mutant gliomas with a known 1p/19q status who had preoperative MRI were included." (PMID 36831380, 2023). "IDH1 and IDH2 mutations have been found in glioma, chondrosarcoma, and AML, according to research by Clark and colleagues." (PMID 36980194, 2023). "Mutations in IDH1 and IDH2 are also common in gliomas, AML, chondrosarcomas, and cholangiocarcinoma." (PMID 36979633, 2023). "This was conducted using the RCAS/TVA system to ectopically express mutant IDH1 (R132H) in PDGF-driven gliomas." (PMID 36765553, 2023). "The proportion of temporal lobe tumors is significantly higher in IDH1-wt glioma, which often has histopathological features of oligodendroglioma." (PMID 37029174, 2023). "Currently, the expression analysis of Isocitrate Dehydrogenase (NADP (+)) 1 (IDH1) and the identification of its main mutations (e.g. R132H) are used for glioma diagnosis and prognosis." (PMID 35654889, 2023). "Yet metabolomic analysis demonstrated higher levels of 2HG and decreased glutamate levels in IDH1 mutant glioma tissue." (PMID 38137775, 2023). "We screened WHO grade 4 glioma patients who received radiotherapy with known IDH1 gene status in the CGGA RNA array database." (PMID 37952042, 2023). "Mutations in the isocitrate dehydrogenase (IDH1/2) enzyme, which is typically found in grade II and III gliomas, result in the accumulation of 2-hydroxyglutarate (2-HG) in tumour cells." (PMID 37238288, 2023).
glioma (continued). "Substitution point mutations in IDH1 (R132H) and IDH2 (R172K; R140Q) are common events in low-grade (II/III) glioma (> 75%) and acute myeloid leukemias (AML) (20%), but rare in other cancers." (PMID 38066546, 2023). "We enrolled 83 WHO Grade 4 glioma patients who received radiotherapy in our center from 2017.1 to 2020.10 to detect IDH1 gene status." (PMID 37952042, 2023). "Single-step growth curves also demonstrated that IDH1(R132H) promoted viral replication in glioma cells." (PMID 37880243, 2023). "Compared to IDH1 wild-type gliomas, IDH1 mutant gliomas exhibit significant metabolic changes, shifting from glycolysis to lipid metabolism." (PMID 38111705, 2023). "A diminished expression of PRMT1 (protein arginine methyltransferase 1) and its target asymmetric dimethyl H4R3 mark in IDH1-MT was concomitant with reduced PTX3 in IDH1-MT glioma cells and in patients." (PMID 37476290, 2023). "A panel of surgically resected samples (IDH1 wild-type glioma N = 4, IDH1 mutant glioma N = 4 and Control/Epilepsy tissue N = 4) were assayed with ChIP-seq for H3K27 modifications (H3K27me3 and H3K27ac)." (PMID 37528157, 2023). "We found a potential network between lncRNA CRNDE, miR-23b-3p, and IDH1, and our in vivo experiments partially confirmed the role of lncRNA CRNDE in promoting glioma metastasis through the regulation of miR-23b-3p/IDH1." (PMID 37934582, 2023). "A phase II study of DS-1001 in patients with chemotherapy- and radiotherapy-naïve IDH1 mutant WHO grade 2 gliomas is ongoing to verify the efficacy of DS-1001 as a single agent (NCT04458272)." (PMID 37296846, 2023). "As a result, an increase in 2HG and a decrease in NADPH, GSH, Glu and Gln levels have been demonstrated in IDH1 mutant gliomas." (PMID 38137775, 2023). "IDH1 and IDH2 are frequently mutated in multiple types of human cancers, including glioma, acute myeloid leukaemia, cholangiocarcinoma, chondrosarcoma, and thyroid carcinoma." (PMID 37980418, 2023). "In the current WHO 2021 classification, IDH1/2-mutant gliomas are further classified into those with a 1p/19q codeletion (oligodendrogliomas grade 2–3) and those without (astrocytomas grade 2–4)." (PMID 37345193, 2023). "The median stiffness depends on glioma cell types and decreases according to the following manner: IDH1 R132H mt (4.7 mN/m), CD44+/IDH1wt (3.7 mN/m), CD44-/IDH1wt (2.5 mN/m)." (PMID 36835465, 2023). "We demonstrate for the first time that PRMT1/H4R3me2a differentially regulates PTX3-driven ferritinophagic flux in IDH1 wild-type and mutant gliomas." (PMID 37476290, 2023). "While further results are needed to evaluate the efficacy of the vaccine in these trials, both suggest a potential therapeutic role for the IDH1-R132H vaccine in IDH-mutant gliomas." (PMID 36768342, 2023). "Here we verified the feasibility of a POCT of the IDH1-R132H (c.395G>A) in frozen and fresh glioma tissue samples based on Crispr-Cas12a." (PMID 37029174, 2023). "In conclusion, the discovery of mutations in the IDH1 and IDH2 genes has revolutionized our understanding of lower-grade gliomas and opened up new avenues for diagnosis and treatment." (PMID 37212938, 2023). "Other trials have studied PARPi in patients with gliomas, but their inclusion criteria likely excluded most patients with IDH1/2mt and/or other homologous recombination defects." (PMID 36968138, 2023). "Noteworthily, compared to primary tumors, recurrent gliomas more frequently exhibit features such as copy number variations (CNV), combined IDH1 and TERT mutations, compromised cell cycle signaling pathways, and low tumor mutational burden (TMB)." (PMID 37760399, 2023). "A brain lesion biopsy revealed a high-grade infra-tentorium IDH-1 and IDH-2 wild-type glial tumor, GFAP and Olig2 positive and histone H3‐K27M mutation-negative (glioblastoma, grade 4 WHO 2021)." (PMID 37692853, 2023).
glioma (continued). "KM survival analysis was performed to compare the OS time between the IDH1-mutant group and the IDH1-wild group, and the result showed that patients with IDH1 mutant gliomas had a better prognosis." (PMID 36837615, 2023). "Accordingly, in vivo data showed that IDH1 mutant glioma cells have increased recruitment of TAM; these data support the anti-tumour functions of TAMs in vivo." (PMID 37296846, 2023). "LDs were found in both glioma types; however, IDH1-wt glioblastoma had more classical LDs in its tumor cells than the IDH1-mt astrocytoma tumors." (PMID 38168422, 2023). "Targeting glutaminase was also confirmed to be an effective means of inhibiting the growth of IDH1 mutant glioma cells." (PMID 36970537, 2023). "Preclinical studies showed delayed tumor growth through small molecule IDH1 inhibition in glioma cells." (PMID 36566461, 2023). "Tissue microarrays of 46 reactive glioses, 81 glioblastomas, 34 IDH1-mutant diffuse gliomas, and 23 gliomas of other types were analysed." (PMID 37568909, 2023). "Within this group of vaccines, the vaccine against the R132H mutation of IDH1 tested in grade III and IV gliomas presenting this mutation, is noteworthy." (PMID 37165457, 2023). "Mutations in the isocitrate dehydrogenase genes (IDH1 and IDH2) define a unique glioma subtype associated with an immunosuppressive tumor microenvironment." (PMID 37543576, 2023). "Immune suppression of the IDH-mutant TME is also related to a reduction in immune cell recruitment, characterized by a reduction in chemotaxis factors compared to IDH1/2 wildtype gliomas." (PMID 37345193, 2023). "A percentage of glioma patients have a drug-refractory epilepsy that requires a second add-on drug (or third ASM), in particular patients with IDH1 mutated glioma." (PMID 37071297, 2023). "Specific antigens discovered in the field of glioma in recent years mainly include epidermal growth factor receptor vIII (EGFRvIII) and mutant isocitrate dehydrogenase 1 (IDH1)." (PMID 36765560, 2023). "Several studies suggest that mutations of isocitrate dehydrogenases (IDH1/2), which represent one of the main characteristics of glioma cells and occur at specific codons in IDH1 and IDH2, are attractive candidates for glioma immunotherapy." (PMID 38274827, 2023). "The peroxisome hallmark geneset notably includes IDH1 and 2, SMARCC1 (also part of Myc targets v1), transcription factors part of PD1 target associated with survival and immune signaling in glioma." (PMID 37637066, 2023). "Isocitrate dehydrogenase 1 (IDH1)-mutated tumors demonstrated a significantly better outcome compared to IDH1-wildtype gliomas in many studies." (PMID 37043120, 2023). "Highlighting that IDH1/2 gene and TERT promoter mutation are related to the prognosis of patients with glioma." (PMID 37250582, 2023). "The authors interpreted the results to suggest that mutant IDH1 is detrimental to the glioma cell of origin and the microenvironment." (PMID 36765553, 2023). "When assessed for response to the pan-HDACi drug belinostat, mutant IDH1-expressing glioma cells were subjected to more potent inhibition of growth than the corresponding control cells." (PMID 37218937, 2023). "To determine the relationship between risk score and clinical characteristics of glioma patients, we analyzed the potential predictors (level of risk, age, gender, WHO grade, 1p/19q, and IDH1 status)." (PMID 38022537, 2023). "One example of this is the identification of mutations in isocitrate dehydrogenase 1 (IDH1) and/or 2 (IDH2) as critical biomarkers for glioma classification and prognosis." (PMID 38026690, 2023).
glioma (continued). "In gliomas carrying mutations in genes encoding isocitrate dehydrogenase 1 (IDH1) or 2 (IDH2), microglia-derived TAMs are more dominant compared to wild-type gliomas." (PMID 37234776, 2023). "Mechanistically, D2HG produced by mutant IDH1 enhances the binding of DNMT1 to IRF3/7 promoters such that IRF3/7 are downregulated, leading to impaired type I IFN response in glioma cells, which enhances the susceptibility of gliomas to viral infection." (PMID 37880243, 2023). "In this IDHwt-IDHmut mouse glioma pairing, the IDHmut cells expressed the IDH1 R132H protein and produced more 2HG." (PMID 37104042, 2023). "Through statistics of the glioma database and patients in our center, we confirmed that IDH1 gene status is indeed related to the efficacy of radiotherapy in glioma patients." (PMID 37952042, 2023). "As NOA-21, a neoadjuvant window-of-opportunity trial in patients with recurrent IDH1-mutant gliomas, INTERCEPT-H3 integrates an immune checkpoint inhibitor to amplify neoepitope-specific T cell responses." (PMID 37853454, 2023). "In summary, our studies provide strong evidence that IDH1 expands glioma immunotherapy benefits, can enhance T cell lysis and responsiveness to multiple tumor antigens, and possesses selective binding and desialylation activity against CD8 dimers." (PMID 37161052, 2023). "The survival analysis was done on a population of 264 IDH1-wildtype grade 4 glioma patients in the survival range of 0.43 to 76.9 months." (PMID 36653382, 2023). "They used two samples of freshly resected low-grade gliomas, with one being an astrocytoma with mutant IDH1 R132C and another being an oligodendroglioma with mutant IDH1 R132H." (PMID 36765553, 2023). "For in vitro experiments, we established glioma cells stably overexpressing IDH1 wild-type and IDH1-mutant proteins." (PMID 37952042, 2023). "The purpose of this study is to explore the potential mechanism of how IDH1 mutation can increase the efficacy of radiotherapy and to establish a risk-score model to predict the efficacy of radiotherapy in WHO grade 4 gliomas." (PMID 37952042, 2023). "Treatment with the IDH1 inhibitor ivosidenib delayed the progression of cancer cachexia in murine GL261 glioma model and CT26 colorectal carcinoma models." (PMID 37741882, 2023). "Of the eleven annotated HDAC enzymes (HDAC1-11) only six are expressed in IDH1 mutant glioma tissue samples and patient-derived gliomasphere lines (HDAC1-4, HDAC6, and HDAC9)." (PMID 37528157, 2023). "With such encouraging results, a randomized phase I trial was initiated to test the IDH1-vac in combination with avelumab, an anti-PD-L1 drug, in the IDH1 mutant gliomas (NCT03893903)." (PMID 36986491, 2023). "In this study, we demonstrate that IDH1 over-expression increases survival time and survivor numbers following vaccine immunotherapy in a glioma model, GL26." (PMID 37161052, 2023). "These strategies were employed by Philip and colleagues to create the first mutant IDH1-driven GEMM of high-grade glioma." (PMID 37051530, 2023). "Primarily, a non-direct method for tissue mechanics in vivo investigation utilizing magnetic resonance elastography displayed the IDH1 R132H gliomas as more rigid than the wild-type ones." (PMID 36835465, 2023). "The most common and most malignant type of glioma (grade four, IDH1/2 wt according to World Health Organisation) is glioblastoma (GBM)." (PMID 37239035, 2023). "The mitochondrial production of proline is enhanced to maintain redox homeostasis in IDH1-mutant glioma cells." (PMID 37108511, 2023). "In this study, we performed a comprehensive ultrastructural analysis of lipid accumulation inside tumor cells and in the tumor microenvironment of two types of gliomas: IDH1-mt astrocytoma and IDH1-wt glioblastoma." (PMID 38168422, 2023).